MEAF6 (MYST/Esa1 associated factor 6)
Description:
Component of the NuA4 histone acetyltransferase complex which is involved in transcriptional activation of select genes principally by acetylation of nucleosomal histone H4 and H2A. This modification may both alter nucleosome - DNA interactions and promote interaction of the modified histones with other proteins which positively regulate transcription. Component of HBO1 complexes, which specifically mediate acetylation of histone H3 at 'Lys-14' (H3K14ac), and have reduced activity toward histone H4. Component of the MOZ/MORF complex which has a histone H3 acetyltransferase activity.
Synonyms: C1orf149; CENP-28; EAF6; NY-SAR-91; FLJ11730
Tractability: PROTAC: UniProt records ubiquitination sites on it; ubiquitination databases record sites on it; its protein half-life has been measured.
Gene: Protein-coding gene on chromosome 1 (37,489,993 to 37,514,806, reverse strand). Ensembl gene ENSG00000163875.
Subcellular location: Nucleus, nucleolus; Chromosome, centromere, kinetochore
Subcellular location (Human Protein Atlas): Nuclear bodies; Nucleoplasm
Pathways (Reactome):
Chromatin organization: HATs acetylate histones
Gene Ontology:
Molecular function: histone H3K14 acetyltransferase activity; histone H4K12 acetyltransferase activity; histone H4K5 acetyltransferase activity; histone H4K8 acetyltransferase activity; protein binding
Biological process: positive regulation of double-strand break repair via homologous recombination; regulation of cell cycle; regulation of cell growth; regulation of DNA biosynthetic process; regulation of DNA replication; regulation of DNA-templated transcription; positive regulation of DNA-templated transcription; regulation of apoptotic process; regulation of developmental process; regulation of double-strand break repair; regulation of hemopoiesis; chromatin remodeling
Cellular component: histone acetyltransferase complex; kinetochore; MOZ/MORF histone acetyltransferase complex; NuA4 histone acetyltransferase complex; nucleolus; nucleoplasm; nucleosome; nucleus
Genetic constraint (gnomAD): Loss-of-function variants: 15 observed, 24.74 expected, observed/expected ratio (o/e) 0.61, 90% interval 0.41 to 0.93. The upper end of that interval is the gene's LOEUF score, 0.93, which puts it in group 3 of 6, group 1 being the genes least tolerant of losing a copy. Missense variants: 178 observed, 229.4 expected, observed/expected ratio (o/e) 0.78, 90% interval 0.69 to 0.88. Synonymous variants: 97 observed, 83.74 expected, observed/expected ratio (o/e) 1.16, 90% interval 0.98 to 1.37.
Homologues: Orthologues: mouse Meaf6 (99% identical), chimpanzee MEAF6 (97% identical), pig MEAF6 (97% identical), dog MEAF6 (97% identical), rat Meaf6 (93% identical), tropical clawed frog meaf6 (93% identical), rabbit MEAF6 (84% identical), zebrafish meaf6 (84% identical), guinea pig MEAF6 (82% identical), macaque MEAF6 (64% identical), Drosophila melanogaster Eaf6 (42% identical), Caenorhabditis elegans B0025.4 (29% identical).
Diseases named in the same sentence as MEAF6 in open-access papers:
MEAF6 is named in the same sentence as 9 diseases in open-access papers, as found by Europe PMC text mining. Sharing a sentence is not in itself a finding about the gene and the disease. The quoted sentences say what the papers report.
endometrial stromal sarcomas (3 papers, 2015 to 2022). "However, the MEAF6-SEPSEC rearrangement detected in one patient, GIST_150, is noteworthy since MEAF6 has recently been reported as translocated with PHF1 in endometrial stromal sarcomas and in ossifying fibromyxoid tumors." (PMID 26544626, 2015). "The fusions reported in endometrial stromal sarcomas (ESS) include JAZF1-SUZ12, YWHAE-FAM22, ZC3H7-BCOR, MBTD1-CXorf67, and fusions of PHF1 with JAZF1, EPC1, and MEAF6." (PMID 35627126, 2022). "Intriguingly, besides AML-related ZM fusion, aberrant chromosomal rearrangements detected in endometrial stromal sarcoma patients recurrently target components of NuA4/TIP60 complex such as EP400, EPC1, EPC2, MEAF6 and MBTD146–50." (PMID 33594072, 2021).
autoimmune disease (1 paper, 2023). A disorder resulting from loss of function or tissue destruction of an organ or multiple organs, arising from humoral or cellular immune responses of the individual to their own tissue constituents. "Briefly, some epitopes belonging to MEAF6, CHL1, and ZHX2 were reported to be potentially presented by either class I or class II HLA alleles for which a clear association with autoimmune diseases has been described." (PMID 37512859, 2023).
lung carcinoma (1 paper, 2017). "In this study, we identify a splice variant of the MYST/Esa1-associated factor 6 (MEAF6) gene, MEAF6-1, that is highly expressed in both t-NEPC tumor biopsies and neuroendocrine cell lines of prostate and lung cancers." (PMID 28427194, 2017).
neoplasia (3 papers, 2012 to 2022). "Through RNA splicing, SRRM4 simultaneously reprograms REST functions to confer a neuroendocrine phenotype in AdPC cells and re-directs MEAF6 functions to stimulate tumor cell proliferation and invasion." (PMID 28427194, 2017). "5′-RACE, RT-PCR, and sequencing showed the presence of an MEAF6-PHF1 chimera in the tumor with exon 5 of MEAF6 being fused in-frame to exon 2 of PHF1 so that the entire PHF1 coding region becomes the 3′ terminal part of the MEAF6-PHF1 fusion." (PMID 22761769, 2012). "In searching for other SRRM4-targeted RNA splicing that may contribute to NEPC progression, we have found a highly expressed splice variant of the MYST/Esa1-associated factor 6 (MEAF6) gene, MEAF6-1, in NEPC tumor samples." (PMID 28427194, 2017).
MEAF6 also shares sentences with these, for which no sentence is quoted: cancer (1 paper); fibromyxoid tumor (1); leukemia (1); metabolic disorder (1); prostate carcinoma (1).